ENSG00000281883 (novel transcript)
Gene: Protein-coding gene on chromosome 13 (43,883,800 to 44,028,526, forward strand). Ensembl gene ENSG00000281883.
Genetic constraint (gnomAD): Missense variants: 110 observed, 162.06 expected, observed/expected ratio (o/e) 0.68, 90% interval 0.58 to 0.8. Synonymous variants: 48 observed, 51.56 expected, observed/expected ratio (o/e) 0.93, 90% interval 0.74 to 1.18.